INS (insulin)
Diseases named in the same sentence as INS in open-access papers (continued):
Sharing a sentence is not in itself a finding about the gene and the disease.
endometrial cancer (continued). "Furthermore, an intake of 30 g of alcohol per day has been shown to improve insulin sensitivity and reduce fasting insulin concentrations, thereby potentially decreasing endometrial cancer risk, although higher intakes do not seem to have these effects." (PMID 20485288, 2010). "Insulin and IGF-1 are each able to induce the expression of EMT biomarkers in endometrial cancer cell lines." (PMID 36052252, 2022). "Insulin signaling pathways up-regulated by circRNA in NK/T-LAHS, endometrial cancer, and hippopotamus signaling are the three most important signal transduction pathways." (PMID 32856037, 2020). "PI3K/Akt regulates insulin/IGF1 signaling, and IRS1/2 expression in patients with endometrial cancer is positively correlated with YAP/TAZ." (PMID 33178014, 2020). "Insulin upregulates TET1 and then upregulates GPER expression, which enhances the sensitivity of endometrial cancer cells to estrogen." (PMID 31440472, 2019). "How insulin and IGF-1 interact with estrogen in signaling pathways to promote the development of endometrial cancer warrants further investigation." (PMID 31440472, 2019). "Increased insulin and IGF-1 can stimulate the proliferation of endometrial cancer cells by binding to IR and IGF-1 receptors (IGF-1R) and activating downstream signaling pathways." (PMID 31440472, 2019). "The expression of insulin and IGF-1 was significantly increased in diabetic patients, and high insulin levels were an independent factor of endometrial cancer." (PMID 31440472, 2019). "The present study was aimed at identifying the entire set of genes that are differentially activated by insulin glargine or detemir, in comparison to insulin and IGF1, in Type 1 and Type 2 endometrial cancer cell lines (ECC-1 and USPC-1, respectively)." (PMID 29615978, 2018). "The present study was designed to identify the entire set of genes that are differentially activated by glargine or detemir, in comparison to native insulin and IGF1, in both Type I and II endometrial cancer cell lines." (PMID 29615978, 2018). "Metformin, an antidiabetic drug, is effective for endometrial cancer through inhibition of the PI3K-Akt-mTOR pathway by activating LKB1-AMPK and reduction of insulin and insulin-like growth factor-1 due to AMPK activation." (PMID 25734181, 2015). "Research shows that the danger of endometrial cancer was not significantly impacted by metformin usage, insulin usage, or other antidiabetic medications." (PMID 40572709, 2025). "Given the intricate connections between insulin, oestrogen, and the IGF system in the context of endometrial cancer, further exploration of hormonal levels could yield valuable insights." (PMID 38339282, 2024). "When combining pairs of mediators together into a single model, we found evidence that an effect of fasting insulin on endometrial cancer was partially mediated by SHBG levels and that an effect of SHBG on endometrial cancer was largely mediated by bioavailable testosterone levels." (PMID 35436960, 2022). "Endometrial cancer patients have been shown to have increased markers of insulin resistance, including higher fasting insulin levels and elevated non-fasting and fasting C-peptide levels." (PMID 30211120, 2018). "We performed a population-based case-control study in Sweden, including 288 endometrial cancer patients and 392 control women and analysed total serum IGF-I, IGFBP-1, IGFBP-3, insulin and BMI levels stratified by disease and hormone replacement therapy status (HRT)." (PMID 14583772, 2003). "In conclusion, our study does not show any evidence of an overall association between endometrial cancer risk and serum levels of IGF-1, IGFBP-1, IGFBP-3, and insulin." (PMID 14583772, 2003). "Interestingly, elevated serum insulin levels have been shown to be present in women with endometrial cancer, compared with those without the disease." (PMID 34359595, 2021).
endometrial cancer (continued). "Secondly, as also stated previously, insulin may act independently via its downstream PI3K/AKT and Ras/MAPK signaling pathways 28 to induce cell proliferation and inhibit apoptosis, thereby promoting endometrial cancer development." (PMID 29533014, 2018). "Based on epidemiological and clinical correlations, we postulated that insulin analogs might elicit non-classical mitogenic and signaling activities in endometrial cancer." (PMID 29615978, 2018). "However, there are limited data regarding insulin/IGF and sex hormone axes protein and gene expression in normal endometrial tissues, and very few studies have examined the impact of endometrial cancer risk factors on endometrial tissue biology." (PMID 27125830, 2016). "Interestingly, we did not detect any cellular atypia or development of endometrial cancer in insulin+hCG-treated rats; however, we did find that multiple cystic glands filled with large amounts of secretory fluid were present in these rats (D2)." (PMID 27461373, 2016). "In summary, we evaluated several major components of the insulin/IGF and sex hormone axes in normal endometrial tissues from women without cancer in order to describe their relationship with endometrial cancer risk factors to further knowledge on potential biological mechanisms." (PMID 27125830, 2016). "However, other studies did not report correlations between endometrial cancer risk, IGF axis components, and insulin levels." (PMID 24904527, 2014). "However, the exact mechanism of metabolic syndrome affecting the occurrence and development of endometrial cancer has not been determined to date, which may be related to the elevation of such metabolites as blood sugar, insulin, insulin-like growth factor and triglyceride in serum." (PMID 31440472, 2019). "Although endometrial cancer has no direct correlation with insulin or IGF levels, additional factors such as ovarian steroid hormones and/or inflammatory cytokines may make it difficult to confirm a single effect of insulin or IGF activation through insulin or IGF serum levels." (PMID 25866823, 2015).
diabetic neuropathy (117 papers, 2009 to 2026). A chronic, pathological complication associated with diabetes mellitus, where nerve damages are incurred due to diabetic microvascular injury involving small blood vessels that supply these nerves, resulting in peripheral and/or autonomic nerve dysfunction. "The dysregulation of sphingolipid metabolism is associated with insulin resistance and neuronal apoptosis, which in turn contribute to diabetic neuropathy." (PMID 38674796, 2024). "In diabetic neuropathy, diabetic rats showed characteristic weight loss due to the insufficient level of insulin that prevented glucose transportation to cells." (PMID 37371821, 2023). "In the current study, balance capability, diabetic polyneuropathy and insulin treatment were less important risk factors for falls than muscle strength and F-CPR." (PMID 35831378, 2022). "Although insulin is considered as a neurotrophic factor and although low-dose insulin can have beneficial effects on diabetic neuropathy, insulin use is associated with diabetic neuropathy in the DIACART study." (PMID 32092076, 2020). "Here, we discuss the current experimental literature related to insulin's role as a potential neurotrophic factor in peripheral nerve function, as well as the possibility that insulin deficiency plays a role in diabetic neuropathy." (PMID 28066166, 2016). "This work provides evidence that the major contributor to diabetic neuropathy is insulin impairment in association with defects in fat metabolism (lipids, adiponectin)." (PMID 24764191, 2014). "Furthermore, the association between insulin use and diabetic neuropathy is likely to be linked to the development of advanced diabetic complications, consistent with previous studies." (PMID 38959204, 2024). "In addition, diabetic neuropathy, macrovascular complications, impaired renal function and insulin treatment were linked to low TLCO." (PMID 28086884, 2017). "Impaired insulin signalling has been implicated in the pathogenesis of diabetic neuropathy." (PMID 27514532, 2016). "In addition to glucotoxicity as a primary pathogenic mechanism, impaired insulin and growth factor signaling are emerging as glucose-independent pathogenic mechanisms of diabetic neuropathy." (PMID 24764191, 2014). "Additionally, recent evidence has demonstrated that insulin may play an important role in Schwann cell physiology and Schwann cell dysfunction has been implicated in diabetic neuropathy." (PMID 28066166, 2016). "This information would be particularly important to better understand the potential role of impaired peripheral nerve insulin signaling in the pathogenesis of diabetic neuropathy and provide new ideas on their underlying mechanisms that the glycaemic hypothesis cannot otherwise fully explain." (PMID 24023699, 2013). "From a pathophysiological perspective, insulin resistance disrupts skeletal muscle metabolism, while diabetic neuropathy and peripheral arterial disease compromise muscle function and mobility, increasing susceptibility to DF." (PMID 41717550, 2026). "Based on bioactivity predictions using PASS Online, 4-propylbiphenyl acts as a glucan endo-1,6-beta-glucosidase inhibitor, α-amylase inhibitor, diabetic neuropathy treatment, and insulin promoter." (PMID 40295205, 2025). "In male diabetic mice implanted with microencapsulated ASPIRIN-engineered cells, ASA regulates insulin expression, restores normoglycemia, alleviates pain and reduces biomarkers of diabetic neuropathy and inflammation." (PMID 40016240, 2025). "Excessive amount of glucose in circulation because of insulin resistance leads to hyperglycemia, which plays a crucial role in the development of diabetic neuropathy through multiple biochemical pathways." (PMID 40205269, 2025). "In diabetic neuropathy, abnormal metabolic rates and insufficient insulin secretion due to pancreatic β-cell damage impair glucose transportation into cells." (PMID 39166118, 2024).
diabetic neuropathy (continued). "Insulin has been shown to have beneficial effects on several manifestations of diabetic neuropathy, including reduction in formalin test hyperalgesia, improvement in sensory and motor nerve conduction velocity, nerve blood flow, and formalin test hyperalgesia." (PMID 38639646, 2024). "Insulin dysregulation is part of the pathophysiology of diabetic neuropathy, but it also produces microvascular pathological changes and cerebral white matter integrity." (PMID 37763194, 2023). "Patients in the case group had a larger waist circumference, a longer duration of T2D, a higher use of insulin, a higher percentage of diabetic complications such as diabetic neuropathy and diabetic foot, and higher HbA1c values compared to the control group." (PMID 37626799, 2023). "In the weighted univariate Cox regression analysis of the 36-month primary patency, the significant factors were long-term cilostazol usage, statin treatment, insulin use, diabetic neuropathy, intervention (bypass/stenting), and DR." (PMID 35317345, 2022). "Honey given along with insulin for six-weeks improved sensory nerve conduction velocity in experimental diabetic neuropathy Wistar rats." (PMID 33449943, 2021). "The clinical parameters age (HR 1.16 per year, 95% CI 1.07–1.26, p < 0.001), diabetic polyneuropathy (HR 3.58, 95% CI 1.44–8.93, p = 0.006) and insulin therapy (HR 3.25, 95% CI 1.21–8.70, p = 0.019) predicted mortality in T2DM patients independently." (PMID 33183273, 2020). "In this analysis the clinical parameters age (HR 1.16 per year, 95% CI 1.07–1.26, p < 0.001), diabetic polyneuropathy (HR 3.58, 95% CI 1.44–8.93, p = 0.006) and insulin therapy (HR 3.25, 95% CI 1.44–8.70, p = 0.019) were significant predictors of mortality." (PMID 33183273, 2020). "In the present study, significant independent clinical predictors of mortality were age, insulin therapy and diabetic polyneuropathy." (PMID 33183273, 2020). "Sleep disordered breathing is a common yet under-researched diabetic neuropathy complication with consequent decreased patients’ productivity, increased insulin resistance, and impaired glycemic control." (PMID 30237691, 2018). "The present study was aimed to investigate the ability of bioactive guided fractions of Z. jujuba root bark and A. reticulata bark along with insulin against painful diabetic neuropathy." (PMID 28381989, 2017). "The present study explains the neuroprotective ability of bioactive fractions of Annona reticulata bark (ARB) and Ziziphus jujuba root bark (ZJ) along with insulin against diabetic neuropathy." (PMID 28381989, 2017). "This study demonstrated the efficacy of local insulin administration on epidermal innervation in several mouse models of diabetic neuropathy, including type 1 diabetes induced by STZ in C57BL/6J, CD-1, and CFW as well as db/db type 2 diabetic mice." (PMID 28066166, 2016). "The results of the present study showed neuroprotective effects of crocin, safranal and insulin in a rat model of diabetic neuropathy." (PMID 26468467, 2015). "Polygenic risk score for C-reactive protein showed a positive association, while that for fasting insulin showed a negative association with neuropathic pain, in individuals with diabetic polyneuropathy." (PMID 39471050, 2025). "Insulin, the endogenous hormone that regulates glycemia, is known to improve corneal re-epithelialization and was shown to trigger epidermal axons regeneration in a mouse model of diabetic neuropathy." (PMID 39076204, 2024). "In addition, it has been found to improve painful diabetic neuropathy by governing oxidative stress, inflammation and insulin sensitivity in diabetic rats." (PMID 36733419, 2023). "Using complications and forms of clinical intervention (i.e., lifestyle modification, metformin treatment, or insulin treatment) as proxies for advanced illness we also found statistically significant associations between the T2D PGS and insulin treatment and diabetic neuropathy." (PMID 35559025, 2022).
diabetic neuropathy (continued). "In addition, LY, eGFR and insulin 1–2 h after the meal were negatively correlated with the severity of diabetic neuropathy and AGEs." (PMID 35443645, 2022). "Also, honey given with insulin for six-weeks improved sensory nerve conduction velocity in experimental diabetic neuropathy Wistar rats." (PMID 33449943, 2021). "In the present study, six-week treatment of honey given with insulin in an experimental model of diabetic neuropathy Wistar rats resulted in improvement of nerve function, which was manifested by reduction in the latency of sensory and motor nerve action potential with near normalization of NSE." (PMID 33449943, 2021). "However, understanding the effects of this modulation with respect to insulin production or a progression to diabetic neuropathy requires further research." (PMID 33658065, 2021). "The impaired regulation of insulin signaling might promote the development of and pain sensation with diabetic neuropathy, which can be alleviated by its functional restoration." (PMID 33343676, 2020). "Moreover, combined treatment with C-peptide and insulin had a significant effect on diabetic neuropathy compared to insulin injection alone." (PMID 30053902, 2018). "Direct insulin administration of insulin at doses insufficient to change plasma glucose was able to prevent and reverse features of diabetic neuropathy (motor conduction velocities and axonal atrophy) in the sural nerves of streptozotocin-induced diabetic mice." (PMID 28191471, 2017). "However, it has been found that effective doses of crocin (30 mg/kg) and safranal (1 mg/kg) enhanced neuroprotective effect of insulin in diabetic neuropathy (Farshid and Tamaddonfard, 2015 ▶)." (PMID 28078246, 2016). "A reduction in peripheral nervous system (PNS) insulin signaling is a proposed mechanism that may contribute to sensory neuron dysfunction and diabetic neuropathy." (PMID 24252636, 2013). "Collectively, these results provide an important step towards understanding how abnormalities in insulin signaling may impact sensory neurons and may also contribute to the development and/or progression of diabetic neuropathy." (PMID 21754917, 2011). "In addition, Ang-2 levels were significantly higher among subjects with insulin therapy, diabetic polyneuropathy, and diabetic macro-angiopathy." (PMID 21699724, 2011). "Also evaluated were: socio-demographic variables; chronological age; exogenous insulin use; smoking habits; fasting glucose test; diabetic neuropathy and anthropometric measures." (PMID 21542924, 2011). "Insulin signalling is essential for sustaining neuronal glucose absorption and energy metabolism, and its resistance interferes with important processes necessary for the health and function of neurons, contributing to the blooming of diabetic neuropathy, especially in those with type 2 diabetes." (PMID 40205269, 2025). "Of note, adiponectin can influence insulin, glucagon, glucose metabolism, TGs and free-fatty acids concentrations, while PPARγ can change accordingly to medium chain ACCs, being involved in antioxidant activity as well as in peripheral nerve injury and diabetic neuropathy." (PMID 37817933, 2023). "Mice with insulin-resistant Schwann cells due to Schwann cell-specific knockout of IR and insulin-like growth factor receptor 1 (IGFR1) showed thinner myelination and the authors hypothesized that insulin resistance in myelinating cells is one of the pathological contributors to diabetic neuropathy." (PMID 36291644, 2022). "This could be due to the diabetic neuropathy/angiopathy and the type of insulin administration." (PMID 32299459, 2020). "Thus, we speculated this insulin-induced sharp drop in serum potassium levels as potentiating the patient's already existing advanced diabetic neuropathy, thereby leading to muscle cramping." (PMID 28993757, 2017). "Finally, insulin can modify myelin protein expression in the setting of diabetic neuropathy." (PMID 28066166, 2016).